EGFR (epidermal growth factor receptor)
Diseases named in the same sentence as EGFR in open-access papers (continued):
Sharing a sentence is not in itself a finding about the gene and the disease.
lung cancer (continued). "Additionally there are EGFR targeting small molecule PROTACs based also on pomalidomide that have showed selective and potent antitumor activities in EGFR-TKI resistant lung cancer cells and can stimulate necrosis and stop cell cycle in H1975 cells." (PMID 35470756, 2022). "Preclinical studies have suggested that EGFR-TKIs combined with the anti-VEGF antibody bevacizumab could enhance tumor activity in EGFR-TKI-resistant lung cancer cells." (PMID 36553449, 2022). "Based on these previous studies, ER-mediated and EGFR-mediated signaling pathways may positively coregulate cancer-related gene expression during lung cancer progression." (PMID 35034634, 2022). "Consistently, clinical studies suggest that EGFR inhibition should not be confined to EGFR mutated lung cancer patients." (PMID 35618721, 2022). "Preliminary results suggested that EGFR wild-type lung cancer cell H1650 and EGFR mutant lung cancer H1975 cells showed poor sensitivity to icotinib with IC50 values of >50 μM, and 3l exhibited stronger killing effects on the lung cancer cell lines than icotinib did." (PMID 36467103, 2022). "Moreover, we found that EGFR is one of the potential target proteins of PLAUR, which is one of the most common mutation targets in lung cancer." (PMID 36091160, 2022). "Numerous studies have confirmed the important role of miRNAs in acquired gefitinib and erlotinib resistance and targeting these miRNAs may be an effective treatment option for lung cancer patients with first-generation EGFR-TKI-resistant." (PMID 36386184, 2022). "EGFR inhibitors have been widely used in treatment of non-small cell lung cancer, in fact, it was the first biomarker identified as a potential therapeutic target for personalized treatment in lung cancer." (PMID 35681244, 2022). "In this study, we investigated the effect of MA on EGFR-TKI-resistant lung cancer cells." (PMID 36712673, 2022). "Emerging evidence has provided two major hypotheses that partly explain the dysregulation of ncRNA expression in EGFR TKI-resistant lung cancer." (PMID 36139582, 2022). "Given this evidence, NSC609077 may not inhibit the growth or migration of gefitinib-insensitive A549 lung cancer cells by attenuating EGFR/PI3K/AKT signaling pathway activation." (PMID 35408854, 2022). "Based on this, it is necessary to find new strategies to target EGFR for the lung cancer treatment." (PMID 35706930, 2022). "In addition to EGFR inhibitors, our results indicated that the L-score was correlated with lung cancer cell line sensitivity to other drugs tested in the GDSC data." (PMID 35016696, 2022). "EGFR is overexpressed in certain human cancers, such as breast and lung cancer." (PMID 36142321, 2022). "Previous research in patients with non‐small cell lung cancer (NSCLC) showed a reduction in the EGFR mutation frequency after chemotherapy, but no reports have been published about the impact of targeted therapy or immune checkpoint inhibitors." (PMID 35231161, 2022). "Additionally, the fact that it promotes resistance against third-generation TK inhibitors in lung cancer indicates its involvement in EGFR signaling." (PMID 35186754, 2022). "For example, in two studies of patients with metastatic renal cell carcinoma receiving anti-VEGF or mTOR-inhibitors and lung cancer receiving EGFR-TKI therapy, patients treated with statins concurrently had improved overall survival compared to statin non-users." (PMID 36017084, 2022). "Moreover, increased numbers of EpCAM+EGFR+ events were detected in both metastatic colorectal cancer patients and lung cancer patients compared to healthy donors." (PMID 36613466, 2022). "Due to the small sample size, the effect of ICIs in lung cancer patients harboring EGFR exon 20 insertion mutations is lacking." (PMID 36119499, 2022).
lung cancer (continued). "In conclusion, our study shows that MA is a novel EGFR-TKI sensitizer in KRAS-mutated and osimertinib-resistant lung cancer cells by suppressing the KRAS-ERK pathway and inducing ferroptosis via suppressing NRF2-SLC7A11 axis and mitochondrial Ca2+ overload induced-FTH1 pathways." (PMID 36712673, 2022). "There were 61 EGFR gene mutation types among 232 lung cancer patients in the coal-producing areas and 43 EGFR gene mutation types among 176 lung cancer patients in the non-coal-producing areas." (PMID 35606799, 2022). "Finally, subgroup analyses were performed to investigate the effects of different cancer stages and EGFR expression on prognosis in patients with single lung cancer and LCF." (PMID 36233811, 2022). "The surface receptors of platelets may be a potential therapeutic target to conquer the resistance development in EGFR mutant lung cancer patients." (PMID 35756605, 2022). "Interestingly, a few months later, another study showed that DRAM1 suppresses the development of lung cancer by promoting autophagy-related EGFR degradation." (PMID 35529878, 2022). "In EGFR-mutant NSCLC cells, SREBP-1 is a key feature of the resistance to gefitinib, which might be a promising target for the treatment of EGFR mutation in lung cancer." (PMID 35912181, 2022). "For example, the combination of osimertinib and alisertinib, an aurora kinase A inhibitor, was used in a phase I clinal trail of EGFR-mutant lung cancer, and a randomized phase III clinical trial of alisertinib was performed for relapsed or refractory peripheral T-cell lymphoma." (PMID 35745617, 2022). "Even though EGFR mutations occur more frequently in non-smokers with lung cancer, managing smokers and former smokers on erlotinib treatment remains challenging clinically." (PMID 35209919, 2022). "Considering that lung cancer consists of heterogeneous tumors carrying distinct targetable driver gene mutations such as KRAS, EGFR, ALK, umbrella study can be perfectly implemented for lung cancer studies to explore the efficacy of different targeted drugs for patients with lung cancer." (PMID 36591460, 2022). "There were 61 distinct types of EGFR gene mutation in 232 lung cancer patients from the coal-producing areas and 43 different kinds of EGFR gene mutation in 176 patients of the non-coal-producing areas." (PMID 35606799, 2022). "MiR-1-3p and miR-206 may also overcome HGF-induced Gefitinib resistance via suppression of c-Met signaling in EGFR mutant lung cancer cells." (PMID 35264191, 2022). "EGFR TKIs are the most commonly used target drugs in EGFR mutant lung cancer patients." (PMID 36619616, 2022). "Gefitinib is an EGFR-targeting compound and is identified to promote the prognosis of lung cancer." (PMID 35911442, 2022). "However, lack of significant clinical benefits with the combination therapy of EGFR-directed monoclonal antibodies with TKIs in EGFR mutant lung cancer patients warrants the need for further evidence." (PMID 35209919, 2022). "EGFR is a transmembrane protein that transduces intracellular growth factor signals, promotes tumor proliferation and metastasis, and is an essential target of current lung cancer therapy." (PMID 36230714, 2022). "MiR-145-5p, another member of the miR-145 family, was also found to be significantly down-regulated in patients with brain metastases from lung cancer; this increased the expression levels of downstream EGFR, octamer-binding transcription factor 4, mucin 1, c-Myc, and tumor protein D52." (PMID 36338717, 2022). "Similarly, MEK inhibition is being assessed clinically to enhance the efficacy of EGFR inhibitor therapy in lung cancer, as both EGFR-intrinsic and extrinsic mechanisms of EGFR inhibitor resistance led to the activation of MEK/ERK signaling." (PMID 35082276, 2022). "In this study we show that several lung cancer cells with diverse mutational Ras status and WT EGFR secrete the chemokine IL-8 in non-stimulated conditions." (PMID 36522309, 2022).
lung cancer (continued). "However, novel strategies such as the targeted therapy of EGFR TKIs and immune checkpoint inhibitors, as alternatives to chemotherapy, bring hope for lung cancer patients." (PMID 35743687, 2022). "Glutamine blockade with JHU083 induces robust anti‐tumor immune responses in “uninflamed” and poorly immunogenic EGFR‐driven lung cancer, and JHU083 may enable EGFR‐driven lung cancer more amenable to immunoprevention and immunotherapies." (PMID 35861366, 2022). "For patients with advanced NSCLC and a positive EGFR gene drive, epidermal growth factor receptor tyrosine kinase inhibitors (EGFR-TKIs) are the current first-line treatment option, but these lung cancer patients still have tumor recurrence and aggressive metastasis." (PMID 36005014, 2022). "Vaccination against EGFR can be one of the venues to prevent lung cancer." (PMID 35861366, 2022). "However, what is the therapeutic effect of postoperative adjuvant therapy with EGFR inhibitors in patients with stage IB-IIA lung cancer?" (PMID 36304772, 2022). "Over the past decades, more and more studies have showed that EGFR mutation is a common driver of tumorigenesis, and lung cancer is no exception." (PMID 36619616, 2022). "Another study revealed the anticancer effect of artesunate on A549 lung cancer cells in in vitro and xenograft study models where the inhibitory effect of this compound involved the down-regulation of EGFR, Akt and ATP binding cassette subfamily G member 2 (ABCG2)." (PMID 35267408, 2022). "Therefore, the in vivo findings were in corroboration with the in vitro results, suggesting that 6b possessed potential anticancer activity against EGFR-dependent lung cancer." (PMID 36080307, 2022). "Lastly, by observing tumor cell lysis of the lung cancer lines H292 (EGFR WT) and H1975 (EGFR L858R/T790M) treated with amivantamab in the presence of human peripheral blood mononuclear cells (PBMCs) in vitro, amivantamab was demonstrated to induce ADCC in a similar fashion to cetuximab." (PMID 34913823, 2022). "However, in the future, 10% of patients with non-smoking NSCLC should be included in different molecular studies, which will show that NSCLC’s origin is more significant than the already known oncogenic drivers of lung cancer, such as EGFR, ALK, or ROS1." (PMID 35203569, 2022). "However, with the development and clinical application of targeted therapy, drug resistance of lung cancer patients to EGFR‐TKIs is the most intractable issue in current." (PMID 35838331, 2022). "However, majority of the available reports suggest that EGFR-mutant lung cancer patients have shown poorer response to ICIs treatment." (PMID 35209919, 2022). "Interestingly, it has been reported that Hsp90 inhibitor NVP-AUY922 contributed to enhanced radiation sensitivity of lung cancer cells resistant to EGFR-tyrosine kinase inhibitors." (PMID 36199626, 2022). "Finally, the combination of MM-121 and cetuximab inhibited growth in HNSCC models, including cetuximab resistant models and in engineered mouse models of lung cancers driven by EGFR T790M-L858R." (PMID 36271429, 2022). "For instance, in epidermal growth factor receptor (EGFR)-mutant lung cancer, activation of the Hippo pathway effector protein YAP, Notch-3/β-catenin signaling, AXL, insulin-like growth factor 1 receptor (IGF-1R), or BIM deletion polymorphism mediates drug persistence to initial EGFR-TKI treatment." (PMID 35228642, 2022). "Beyond hepatocellular carcinoma, the lung targeting SORT LNP formulation in combination with an EGFR targeting antibody, and lung cancer specific miRNA signatures could be evaluated for the delivery of NSs." (PMID 35393569, 2022). "However, among those lung cancer patients treated with EGFR-TKIs, many have shown a distinctive response in osteosclerotic change after bone destruction due to metastasis." (PMID 36581856, 2022).
lung cancer (continued). "In addition, EGFR alterations were detected in 36.1% of all ctDNA-positive samples; this was driven by the large proportion of lung cancers among clinical samples." (PMID 35486650, 2022). "The anti-EGFR vaccine resulted in a 76.4% reduction in EGFR-induced lung cancer in mice." (PMID 35814435, 2022). "The field of EGFR TKI resistance research has identified many ncRNAs interacting with oncoproteins, which may directly relieve the trigger of downstream signaling in EGFR TKI-resistant lung cancer and thereby reduce drug sensitivity." (PMID 36139582, 2022). "Patient data revealed that a subset of PTPRH mutant lung cancer did have elevated EGFR activity." (PMID 36054194, 2022). "EGFR is widely amplified in various cancers, such as lung cancer and glioblastoma." (PMID 35931120, 2022). "CT is a routinely used and relatively economical modality for diagnosing lung cancer, and it presents a variety of imaging features that may be used to identify patients with NSCLC who are at risk for EGFR mutations." (PMID 35422977, 2022). "Of the 132 patients with non-EPE lung cancer, older patients, small cell carcinoma and EGFR mutations appeared to be slightly more common than EPE." (PMID 34170380, 2022). "The ERBB/EGFR signaling pathway is also dysregulated in lung cancer." (PMID 36619616, 2022). "An important mediator of pleural effusion in patients with lung cancer is VEGF-A, which promotes neovascularization, increases vascular permeability, and may be associated with resistance to EGFR TKIs." (PMID 36438852, 2022). "Meanwhile, the effect of SHC1 and EGFR on lung cancer was analyzed." (PMID 35706930, 2022). "This study aimed to establish a predictive nomogram integrating epidermal growth factor receptor (EGFR) mutation status for 3‐ and 5‐year overall survival (OS) in unresectable/inoperable stage III non‐small cell lung cancer (NSCLC) treated with definitive chemoradiotherapy." (PMID 34927371, 2022). "A recent study identifies that palbociclib could sensitize lung cancer cells to EGFR-TKI and gefitinib." (PMID 35686110, 2022). "Furthermore, the activation of EGFR in lung cancer cells activated AKT by recycling EGFR to the membrane in gefitinib-resistant cells." (PMID 35681787, 2022). "We propose that EGFR-mut versus EGFR WT lung cancers represent a coordination game." (PMID 35061724, 2022). "EGFR mutations are closely related to lung cancer in never smokers, whereas mutations in KRAS are strongly associated with lung cancer in people who are smoking." (PMID 36118777, 2022). "While our retrospective biomarker analysis was fairly comprehensive, it is limited due to several factors, including that many lung cancers were diagnosed before molecular testing for biomarkers, such as EGFR, ALK, ROS1 and others, were considered standard of care." (PMID 35805276, 2022). "Among clinical studies that used the first-generation EGFR-TKI gefitinib, one study of first-line therapies in patients with EGFR-positive lung cancer and good PS reported a PFS of 10.8 months, whereas another conducted in patients with poor PS reported a shorter PFS of 6.5 months." (PMID 34643820, 2022). "In conclusion, SHC1 and EGFR are expected to become new therapeutic targets for lung cancer." (PMID 35706930, 2022). "In lung cancer, the combination of cfDNA analysis and CTCs for EGFR mutation evaluation using VTX-1 liquid biopsy system (Vortex Biosciences) has enabled the analysis of EGFR mutations in both CTCs and cfDNA from a single blood collection." (PMID 35347327, 2022). "Next, we explored whether EGFR-mutant lung cancer cells could secrete CXCL10 when cocultured with activated PBMCs." (PMID 36612121, 2022).
lung cancer (continued). "Higher vegetable consumption was significantly associated with a lower risk of EGFR + lung cancer (OR = 0.69, 95% CI = 0.54–0.88), however, this association was not significant among EGFR wild-type (−) lung cancer." (PMID 36530673, 2022). "Moreover, the authors observed potentiated growth inhibitory effects of the first-generation EGFR inhibitor gefitinib upon treating lung cancer cells with SCD1 blockers." (PMID 35159223, 2022). "In addition, overexpression of AURKs is related to antineoplastic drug resistance, particularly platinum compounds and EGFR-TKIs in the case of lung cancer." (PMID 36387232, 2022). "Therefore, the combination of EGFR or SFK/FAK inhibitors constitutes a promising therapeutic strategy for EGFR-mutant lung cancer." (PMID 35820889, 2022). "We use differences in patterns of Darwinian selection for critical genes in mutant EGFR (EGFR-mut), mutant KRAS (KRAS-mut), and non-EGFR/KRAS (NEK) lung cancers to identify variations in their evolutionary arcs and associated co-adaptations that govern their molecular characteristics." (PMID 36612014, 2022). "In addition, we experimentally demonstrated that the combination of IDH inhibitors and EGFR TKIs inhibited lung cancer cell proliferation, which provided novel clues for the clinical management of IDH mutants and especially targeted therapy‐resistant patients." (PMID 35526267, 2022). "Thus, for example, the MAPKs pathway is responsible for tamoxifen resistance in ER-positive breast cancer, and the AKT pathway plays role in desensitizing EGFR-overexpressing lung cancer to gefitinib." (PMID 36276073, 2022). "Taken together, these results suggest that EGFR/HER2 inhibitors are potential therapeutic options for BCAR4 fusion-harboring lung cancer patients, even in the absence of EGFR mutations." (PMID 36081848, 2022). "Thus, combining EVax with JHU083, an orally bioavailable glutamine antagonist prodrug will provide optimal efficacy to prevent EGFR‐driven lung cancer development and progression." (PMID 35861366, 2022). "It is widely accepted that epidermal growth factor receptor (EGFR) over-expression in lung cancer cells is associated with tumor progression, still in the lack of specific EGFR mutations." (PMID 35155258, 2022). "However, results on the survival and adverse outcomes even after long-term use of adjuvant EGFR TKI in patients with stage IIA–IIIB lung cancer are still inadequate." (PMID 35360423, 2022). "Western blot analysis indeed revealed that Daidzein and Gefitinib combination treatment synergistically inhibited multiple EGFR phosphorylation sites (P-EGFR Y1068, T845 and T1092) in both A549 and H1975 lung cancer cells, which led to deactivation of STAT1 and STAT3." (PMID 35813479, 2022). "Currently, osimertinib is used as a first-line therapy for EGFR-positive lung cancer." (PMID 34643820, 2022). "However, it is hard to reconcile pre-existing resistance with remission that lasts for months and years before re-emergence of rapidly growing tumors (most patients on front line therapies in ALK+ and EGFR mutant lung cancers)." (PMID 35078159, 2022). "Gefitinib and panobinostat may be effective against gefitinib-resistant lung cancer cells that exhibit mutations in KRAS and EGFR." (PMID 36263432, 2022). "In this study, we propose a personalized drug response prediction model (PDRP), based on molecular dynamics simulations and machine learning, to predict the response of first generation FDA-approved small molecule EGFR-TKIs, Gefitinib/Erlotinib, in lung cancer patients." (PMID 36344580, 2022). "In lung cancer, the use of EGFR tyrosine kinase inhibitors (EGFR-TKIs) is now a common practice for the first-line treatment of patients with EGFR sensitizing mutation, leading to longer progression-free survival (PFS) intervals with fewer or at least different side effects than chemotherapy." (PMID 35402275, 2022).